SDHAF2 (succinate dehydrogenase complex assembly factor 2)
Description:
Plays an essential role in the assembly of succinate dehydrogenase (SDH), an enzyme complex (also referred to as respiratory complex II) that is a component of both the tricarboxylic acid (TCA) cycle and the mitochondrial electron transport chain, and which couples the oxidation of succinate to fumarate with the reduction of ubiquinone (coenzyme Q) to ubiquinol. Required for flavinylation (covalent attachment of FAD) of the flavoprotein subunit SDHA of the SDH catalytic dimer.
Synonyms: C11orf79; PGL2; SDH5; FLJ20487; PPGL2; hSDH5
Tractability: Small molecule: a structure with a bound ligand is known. PROTAC: ubiquitination databases record sites on it.
Gene: Protein-coding gene on chromosome 11 (61,430,042 to 61,446,839, forward strand). Ensembl gene ENSG00000167985.
Subcellular location: Mitochondrion matrix
Subcellular location (Human Protein Atlas): Cytosol; Mitochondria; Nucleoli
Pathways (Reactome):
Metabolism: Maturation of TCA enzymes and regulation of TCA cycle
Gene Ontology:
Molecular function: protein binding
Biological process: mitochondrial respiratory chain complex II assembly; negative regulation of canonical Wnt signaling pathway; negative regulation of epithelial to mesenchymal transition; protein dephosphorylation; protein-FAD linkage; mitochondrial electron transport, succinate to ubiquinone; tricarboxylic acid cycle
Cellular component: mitochondrial matrix; mitochondrion
Genetic constraint (gnomAD): Loss-of-function variants: 21 observed, 18.73 expected, observed/expected ratio (o/e) 1.12, 90% interval 0.79 to 1.61. The upper end of that interval is the gene's LOEUF score, 1.61, which puts it in group 6 of 6, group 1 being the genes least tolerant of losing a copy. Missense variants: 195 observed, 211.4 expected, observed/expected ratio (o/e) 0.92, 90% interval 0.82 to 1.04. Synonymous variants: 84 observed, 75.73 expected, observed/expected ratio (o/e) 1.11, 90% interval 0.93 to 1.33.
Gene-disease validity (ClinGen):
ClinGen rates the evidence that SDHAF2 causes each of these diseases.
hereditary pheochromocytoma-paraganglioma (autosomal dominant): Definitive. Neoplasm predisposition characterized by an increased risk of paragangliomas (tumors that arise from neuroendocrine tissues distributed along the paravertebral axis from the base of the skull to the pelvis) and pheochromocytomas (paragangliomas that are confined to the adrenal medulla).
Cancer hallmarks: escaping immune response to cancer; invasion and metastasis (suppresses); escaping programmed cell death (suppresses); genome instability and mutations; change of cellular energetics
Homologues: Orthologues: macaque SDHAF2 (99% identical), chimpanzee SDHAF2 (98% identical), rabbit SDHAF2 (90% identical), rat Sdhaf2 (90% identical), dog SDHAF2 (89% identical), pig SDHAF2 (88% identical), guinea pig SDHAF2 (87% identical), mouse Sdhaf2 (87% identical), tropical clawed frog sdhaf2 (54% identical), zebrafish sdhaf2 (54% identical), Drosophila melanogaster CG14757 (40% identical), Drosophila melanogaster CG12895 (39% identical), and 1 more.